GP2 (glycoprotein 2)
Diseases named in the same sentence as GP2 in open-access papers (continued):
Sharing a sentence is not in itself a finding about the gene and the disease.
tumor (continued). "GP2 displayed high tumor purities (Kruskal–Wallis test, p < 2.2e-16) and increased metabolism-related pathways, including the TCA cycle and respiratory chain, amino acid metabolism, mitochondrial translation, lipid metabolism, and glycolysis/gluconeogenesis (q < 0.05)." (PMID 35440542, 2022). "This shows that GP2 can be used as a serum tumor marker for the early monitoring of HCC." (PMID 35267641, 2022). "Finally, the results indicated that the in vivo anti-tumor efficacy of the phage delivery system was mediated by the induction of tumor protection in BALB/c mice vaccinated with gpD::GP2 nanoparticles." (PMID 30778090, 2019). "In conclusion, we demonstrated that compared to the control groups, the delivery of GP2 peptide displayed on a non-pathogenic λ bacteriophage, significantly enhanced the anti-tumor immune function in BALB/c TUBO mice model." (PMID 30778090, 2019). "In accordance with in vivo results obtained in IFN-γ, ELISA and cytotoxicity assays, immunization of mice with gpD::GP2 nanoparticles could prevent the TUBO tumor development in mice." (PMID 30778090, 2019). "This analysis showed that in 9 of 14 individuals, the lowest levels of the GP2-immune-metagene signature were in liver metastases, and in many of these individuals, this immune signature is lower in the liver metastases than in the matched primary tumor but is often higher in lung metastases." (PMID 36585450, 2023). "Of interest, these HER2-overexpressing patients had previously received trastuzumab, a HER2-directed monoclonal antibody, as their standard-of-care chemotherapy regimen, suggesting that prior trastuzumab therapy may sensitize tumor cells to cell-mediated lysis triggered by GP2." (PMID 36679991, 2023). "Of note, primary PCa tumours showed high JAG1, GP2, GLO1, NPR3, VGLL3, CHRNA2 and SEMA3F mRNA levels in primary PCa tissue samples." (PMID 40219635, 2025). "Bacteriophage λ displaying a HER2/neu derived peptide GP2 was constructed and used as an anti-cancer vaccine in a BALB/c mouse xenograft tumor model." (PMID 30778090, 2019). "Seven of the twelve differential genes found amongst individual tumor ANOVA analyses were common to the linear discriminant gene profile (LD-p54): ANGPLT4, COL1A1, GP2, GPR57, LAMB3, PCDHB9, and PTGER3." (PMID 15836779, 2005). "However, this strategy often requires the use of HLA-A*02:01-restricted peptides, such as E75 (HER2/neu 369-377) and GP2 (HER2/neu 654-662), to activate T cells, in order to enhance their ability to effectively kill tumor cells." (PMID 41346710, 2026). "GCs from the Gp2 class showed non-statistically significant trends for higher PD-L1 expression at the tumor periphery and pericyte coverage of vessels (after the Bonferroni correction test)." (PMID 37577519, 2023). "GP2 and Lip-DOPE-MPL vaccination groups could promote the induction of INF-γ against tumor compared to other groups (p<0.05)." (PMID 29045460, 2017). "All in all, our findings showed that the presence of co-stimulator molecules such as MPL and DOPE with antigenic properties of GP2 enhanced the ability of APCs to induce the IFN-γ producing CD8+ cells and increased the level of IFN-γ as a major anti-tumor and Th1 type immunity cytokine." (PMID 29045460, 2017). "Due to the absence of GP2 antigen in Lip-DOPE-MPL, this formulation would not induce considerable CTL response and long term protective immunity against her2/neu tumor in mice." (PMID 29045460, 2017).
cancer (13 papers, 2013 to 2025). A tumor composed of atypical neoplastic, often pleomorphic cells that invade other tissues. "Recent studies revealed that patients vaccinated with GP2+ GM-CSF presented with a considerable reduction (37%) in the recurrence of cancer compared to untreated patients, and those patients that received GM-CSF alone presented with a 57% lower risk of cancer recurrence." (PMID 30778090, 2019). "We have advanced this idea by elucidating the role of B-cells in cancer vaccination by designing a chimeric antigenic peptide possessing both cytotoxic T lymphocytes (GP2) and B-cell (P4) peptide epitopes derived from HER2/neu." (PMID 34638441, 2021). "A. Representation of a situation where GP1 genes are favored and GP2 are disfavored by the codon employment, as in cancer." (PMID 31288782, 2019). "The aim of this study was to generate a cancer vaccine based on immunogenic GP2 peptide with the effective adjuvant using a suitable delivery system." (PMID 29045460, 2017). "In this study, we used GP2 peptide conjugated to the DOPE-based pH-sensitive liposomes in the presence of MPL as an adjuvant for the anti-cancer vaccine." (PMID 29045460, 2017). "However, multiple in vitro and phase I and II studies have reported that GP2 is as effective as E75 in terms of inducing an HER2-specific immune response, making GP2 a promising antigen for an HER2-positive cancer vaccine application." (PMID 36551661, 2022). "However, ACE2/GP2 (R 0.108 in normal and R −0.045 in cancer) and FURIN/GAPDH (R −0.198 in normal and R 0.023) present differential correlations between normal and cancer samples." (PMID 33796097, 2021). "GP2 peptide as a TAA has broad applicability as a cancer immunogen with low toxicity." (PMID 29045460, 2017). "In this study, we aimed at developing a liposomal vaccine composed of DMPC- DMPG- Chol- DOPE containing MPL with Gp2 peptide conjugated to the surface of liposomes to increase the CTL response and cellular immunity in the BALB/c mice model of TUBO xenograft cancer." (PMID 29045460, 2017). "Three isoforms GP2, RNASE4 and ADRA2A amongst top down-regulated genes are not reported to be differentially expressed in cancer." (PMID 28330331, 2016).
bacterial infection (4 papers, 2022 to 2025). "Based on these characteristics of omcin genes, we hypothesized that their functions are similar to that of uromodulin and GP2, whose encoded proteins bind to and control bacterial infections in urinary and intestinal tract." (PMID 39309883, 2024). "While zgc153932 does not have a matching homolog in the mammalian genomes, it showed sequence similarity to uromodulin and Glycoprotein2 (GP2), which are epithelial proteins controlling bacterial infection." (PMID 39309883, 2024). "Furthermore, it indicates that the branch-free GP2 filaments constitute the main population in the small intestine of donor 2, underscoring the importance of high-mannose N-glycosylation sites on the filament core for protection against bacterial infections in this particular case." (PMID 40550004, 2025).
inflammation (3 papers, 2021 to 2024). Aberrant reaction of the microcirculation characterized by movement of fluid and leukocytes from the blood into extravascular tissues. "As demonstrated in the present study, GP2 is a key mucosal defensive molecule, especially under the pathological condition of intestinal inflammation when the mucus layer is reduced, that binds to commensal bacteria and prevents their adhesion and invasion into the intestinal epithelium." (PMID 33594081, 2021).
gastrointestinal disorders (2 papers, 2024). "Whereas older individuals exhibited lower GP2-levels they are expected to have a higher risk of developing gastrointestinal disorders, potentially causing dysbiosis." (PMID 39427219, 2024).
benign tumor (1 paper, 2025). "To obtain human-derived GP2 filaments, we collected surgically excised pancreas tissue from a patient with pancreatic masses (donor 1), which were later diagnosed as a benign tumor." (PMID 40550004, 2025).
intestinal diseases (1 paper, 2022). "Further studies should focus on the occurrence and function of GP2 during intestinal diseases." (PMID 35020452, 2022).
GP2 also shares sentences with these, for which no sentence is quoted: melanoma (3 papers); chronic kidney disease (2); Hypertension (2); ischemic stroke (2); acute myeloid leukemia (1); AIDS (1); Alveolitis (1); amyotrophic lateral sclerosis (1); Anxiety (1); autoimmune hemolytic anemia (1); autoimmune pancreatitis (1); bile duct cancer (1); brain tumors (1); cardiovascular disease (1); chronic pancreatitis (1); cryptosporidiosis (1); dementia (1); endometrial cancer (1); Erythema (1); fatty liver disease (1); giardiasis (1); heart disease (1); Insulin resistance (1); intestinal inflammation (1); malignant brain tumors (1); meningioma (1); metabolic disease (1); multiple sclerosis (1); Myoclonus (1); Parkinsonism (1).
A further 7 diseases each share a sentence with GP2 in 1 paper.